MSH6 (mutS homolog 6)
Diseases named in the same sentence as MSH6 in open-access papers (continued):
Sharing a sentence is not in itself a finding about the gene and the disease.
small bowel cancers (7 papers, 2018 to 2025). "Among extra-intestinal cancers’ risk, preliminary data suggest a significantly in-creased risk of small bowel cancers especially in IBD with LS and specifically associated with defects in MLH1 and MSH6." (PMID 39272825, 2024). "The number of affected individuals with small bowel cancer (n = 0), skin cancer (n = 1) and urinary tract cancer (n = 10) was too limited for analysis in the MSH6 group." (PMID 30386444, 2018). "No cases of small bowel cancer were observed in MSH6 carriers." (PMID 30386444, 2018).
astrocytoma (6 papers, 2013 to 2025). "Univariate survival analysis revealed that loss of MSH6 expression was significantly associated with a better median OS in high-grade astrocytomas (13.8 months vs. 10.1 months)." (PMID 24073290, 2013). "Furthermore, survival analysis showed that loss of MSH6 expression was significantly associated with longer overall survival in high-grade astrocytoma patients in our series." (PMID 24073290, 2013). "An astrocytoma CNS WHO grade 4 of a patient carrying a homozygous MSH6 germline frameshift variant, i.e. NM_000179.3(MSH6):c.691del p.(V231Yfs*15), had a TMB of 42.2 mut/Mb and served as positive control." (PMID 37990341, 2023). "We further analyzed the differences between the study cohort and the validation cohort of patients in order to unravel the role of MSH6 protein expression in patients diagnosed of astrocytoma." (PMID 24073290, 2013). "In order to validate the prognostic value of MSH6 expression on high-grade astrocytomas survival, we evaluated MSH6 protein expression in an independent cohort of 71 high-grade astrocytomas." (PMID 24073290, 2013). "In our series, loss of MSH6 expression confers a better prognosis in high-grade astrocytomas treated only with radiotherapy suggesting that MSH6 protein could modulate response to radiation therapy in these tumors." (PMID 24073290, 2013). "Furthermore, multivariate Cox model indicated that MSH6 expression, age and treatment were statistically significant independent prognostic factors for OS of high grade-astrocytomas in our series." (PMID 24073290, 2013). "Nevertheless, MSH6 alterations have also been documented in pretreated astrocytoma tumors." (PMID 24073290, 2013). "We must note that all cases included in our study were analyzed before therapy, confirming that loss of MSH6 expression in astrocytomas is not always secondary to therapy-induced mutagenesis." (PMID 24073290, 2013). "Therefore, our results indicate that MSH6 expression might constitute a prognostic marker for astrocytoma survival in patients treated only with radiotherapy." (PMID 24073290, 2013). "Interestingly, survival analysis identified that tumors lacking MSH6 expression presented longer overall survival in high-grade astrocytoma patients treated only with radiotherapy while MSH6 expression did not modify the prognosis of those patients treated with both radiotherapy and chemotherapy." (PMID 24073290, 2013).
bowel cancer (6 papers, 2018 to 2026). "In this case-control study, mutations in 8 genes (APC, ATM, MLH1, FANCD2, MSH3, MSH6, PMS1, and RAD51D) were found to be associated with bowel cancer and were present in 3.5% of patients with bowel cancer." (PMID 35154239, 2021). "Carriers were further categorised into those who had a FDR with bowel cancer (FH+; n = 45 for MLH1, n = 39 for MHS2 and n = 114 for MSH6) and those who did not (FH-; n = 44 for MLH1, n = 32 for MHS2 and n = 307 for MSH6)." (PMID 37936660, 2023).
cholangiocarcinoma (6 papers, 2017 to 2024). A carcinoma that arises from the intrahepatic biliary tree (intrahepatic cholangiocarcinoma) or from the junction, or adjacent to the junction, of the right and left hepatic ducts (hilar cholangiocarcinoma). "The query revealed six Subjects (Subject 5 - Subject 10) positive for germline VUS in PMS2 or MSH6 genes who had non-Lynch related tumors of cholangiocarcinoma, lung adenocarcinoma, clear cell renal cell carcinoma, serous type endometrial adenocarcinoma, and urothelial carcinoma." (PMID 36091175, 2022).
hereditary colorectal cancer (6 papers, 2014 to 2025).
polyposis (6 papers, 2015 to 2024). "Fourteen relatives, all unaffected by cancer or polyposis, were genotyped for these MSH6 and MUTYH variants, identifying one additional carrier of both variants, five MSH6‐only carriers and four MUTYH‐only carriers." (PMID 32615015, 2020). "Patient B had polyposis from 35 year of age and was diagnosed with an MMR-deficient CRC at 42 (MSI and loss of MSH6 protein) as well as cancer in small intestine (jejunum and duodenum) at age 54 and 57, respectively." (PMID 36856825, 2023).
rectal tumor (6 papers, 2007 to 2026). "Furthermore, other somatic mutations of MSH6 (c.3284G>A, c.676G>T) were detected in this patient's rectal tumors, suggesting that the frequency and type of secondary mutation strikes may differ among organs, resulting in the atypical phenotype of dMMR and MSI." (PMID 36591511, 2022).
serous ovarian cancer (6 papers, 2010 to 2025). "Increased MSH6 and PMS2 mRNA expression was correlated with a favorable overall survival in serous ovarian cancer patients." (PMID 29063235, 2018). "Interestingly, our date showed that increased MSH6 and PMS2 mRNA levels were correlated with a favorable OS in serous ovarian cancer, but not in endometrioid ovarian cancer." (PMID 29063235, 2018).
skin cancer (6 papers, 2017 to 2024). "The MSH6 c.3182T>C, p.(Leu1061Pro) variant, was found in patient OC79, who was diagnosed with endometrioid OC at 49 years old and has two relatives affected by colorectal and skin cancer." (PMID 33008098, 2020).
acute myeloid leukemia (5 papers, 2019 to 2023). Acute myeloid leukemia (AML) is a group of neoplasms arising from precursor cells committed to the myeloid cell-line differentiation. "A child having biallelic MSH6 mutations was reported to have MB at the age of 7, acute myelocytic leukemia at 10 years, and coloric polyps/carcinoma at 13 years." (PMID 32168907, 2020). "However, in the expression level of MSH6 between tumor and adjacent normal tissues in other tumors, we did not obtain significant differences, including LAML (Acute myeloid leukemia), ACC (Adrenocortical carcinoma) or OV (Ovarian serous cystadenocarcinoma)." (PMID 34941572, 2021).
diffuse large B-cell lymphoma (5 papers, 2021 to 2023). "We describe a case of a boy with neurodevelopmental delay and a diffuse large B-cell lymphoma (DLBCL) in whom we discovered a germline de novo 2p16.3 deletion including MSH6 and part of the FBXO11 gene." (PMID 33811277, 2021). "In conclusion we present a case of a boy with developmental delay resulting from a de novo germline 2p16.3 deletion including FBXO11 and MSH6, who developed a diffuse large B-cell lymphoma." (PMID 33811277, 2021).
mucinous adenocarcinoma (5 papers, 2014 to 2025). An invasive adenocarcinoma composed of malignant glandular cells which contain intracytoplasmic mucin. "MSH6 loss was predominantly observed in signet-ring cell adenocarcinomas and mucinous adenocarcinomas." (PMID 40941629, 2025). "Specifically, MSH6-negative status was found in 20% of signet-ring cell adenocarcinomas, 6.5% of mucinous adenocarcinomas, 0.8% of adenocarcinomas NOS, and 0% of neuroendocrine tumors (p = 0.001)." (PMID 40941629, 2025).
mutyh-associated polyposis (5 papers, 2013 to 2022). An autosomal recessive hereditary neoplastic syndrome caused by mutations in the MUTYH gene on chromosome 1p34.1. "MUTYH mutations are the cause of MUTYH-associated Polyposis (MAP) and monoallelic MUTYH missense mutations have been suggested to confer an increased CRC risk when combined with MSH6 mutations." (PMID 24040339, 2013).
ovarian endometrioid carcinoma (5 papers, 2020 to 2023). "A maximum of six mutations was present in one patient with endometrioid ovarian carcinoma (MSH6, PIK3CA, FBXW7, PIK3R1, PITCH1, ERBB3 and PPP2R1A)." (PMID 32120793, 2020).
prostate tumours (5 papers, 2016 to 2025). "The sample that scored the lowest fraction of unstable loci (22 and 27% in duplicate analysis) was an MSH6 deficient prostate tumor, which showed a more subtle shift in the pentaplex PCR analysis compared to other positive controls." (PMID 32264863, 2020). "Near to complete loss of MSH6 immunoreactivity in the prostate tumour supports silencing of the remaining MSH6 allele during prostate carcinogenesis." (PMID 27456091, 2016). "On the other hand, as no loss of MSH6 expression was observed in the prostate tumor, this MSH6 variant is unlikely to explain the PrCa predisposition in this family, which is most likely related to the RAD51C truncation mutation or the ATM missense mutation also found in this patient." (PMID 29659569, 2018).
sebaceous adenoma (5 papers, 2021 to 2025). A benign, well circumscribed neoplasm arising from the sebaceous glands. "The LS was diagnosed when he presented with multiple sebaceous adenomas and genetic testing showed a pathogenic variant in MSH6 mismatch repair gene." (PMID 33977078, 2021).
sebaceous cancer (5 papers, 2020 to 2024).
sebaceous tumors (5 papers, 2021 to 2024).
urothelial carcinoma (5 papers, 2016 to 2022). A malignant neoplasm derived from the transitional epithelium of the urinary tract (urinary bladder, ureter, urethra, or renal pelvis). "The bladder tumor reported in case 2 was a hypodifferentiated uroepithelial carcinoma with MSH6-expression deficiency and MSI-L." (PMID 36591511, 2022). "All of the 21 TMB-high tumors were classified as MSI by NGS except for one “false-negative” case: a urothelial carcinoma in LS with isolated loss of MSH6, MSI with MSI-PCR, and 37 mut/Mb." (PMID 34545179, 2022).
uterine cancer (5 papers, 2020 to 2024). Primary or metastatic malignant neoplasm involving the uterine corpus and/or the cervix. "The MSH6 inframe variant c.3848_3862del, p.(Ile1283_Tyr1287del), was identified in patient OC24, a woman diagnosed with endometrioid OC and uterine cancer at 51 years old, whose family has a history of colorectal, breast, and liver cancer." (PMID 33008098, 2020).
colorectal adenoma (4 papers, 2019 to 2024). An adenoma that arises from the colon or rectum.
dysplasia (4 papers, 2018 to 2026). A usually neoplastic transformation of the cell, associated with altered architectural tissue patterns. "It has been suggested that deletion of MSH-2 and MSH-6 expression is associated with right colon location, dysplasia, and mucinous differentiation, and our results pointed out that MSH-2 positivity was associated with a 4.815-fold increase in the risk of LNM." (PMID 40247833, 2025). "In the present study, the elevated levels of MSH6 determined in the discovery experiment were confirmed by significantly increased MSH6 IHC staining in dysplasia/EAC." (PMID 34227026, 2021).